CDKN2B (cyclin dependent kinase inhibitor 2B)
Diseases named in the same sentence as CDKN2B in open-access papers (continued):
Sharing a sentence is not in itself a finding about the gene and the disease.
melanoma (continued). "These include some canonical melanoma tumor-suppressive genes such as BRD9 and CDKN2A/CDKN2B, and several critical melanoma oncogenes like BIRC5 and YAP1." (PMID 37904237, 2023). "For example, the RB1 pathway is a primary driver of skin cancers, with mutations in RB1, CDKN2A/p16, CDKN1A/p21, CDKN1B/p27, CDKN2B/p15, CCNE1/cyclin E, and CCND1/cyclin D, collectively, in 26.4% of melanomas." (PMID 34983823, 2022). "A later study utilizing melanoma cell lines across different stages of melanoma progression implicated sequential loss of Cyclin Dependent Kinase Inhibitor genes CDKN2A and CDKN2B with CA." (PMID 36276131, 2022). "We first looked at an extended list of high-risk genes predisposing to melanoma (ACD, CDKN2A, CDK4, POT1, TERF2IP, and TERT) or RCC (CDKN2B, FH, FLCN, MET, PBRM1, PTEN, SDHs, TSCs, and VHL) or both (BAP1 and MITF)." (PMID 34067022, 2021). "Common putative risk genes for RCC and melanoma – BAP1, MITF, CDKN2B – suggest that similar pathways are disrupted in both disorders; however, individual variant risks should be evaluated when shared genetic background is taken into account." (PMID 33051548, 2020). "Studies have demonstrated that CDKN2B is deleted in a wide spectrum of tumors including melanoma, pancreatic adenocarcinoma, glioblastoma, certain leukemias, non-small cell lung cancer, and bladder carcinoma." (PMID 31736743, 2019). "A large duplication of the CDKN2A/CDKN2B loci has also been reported in a melanoma patient from a Swedish family, but the clinical significance of this variant is not evident." (PMID 18612309, 2008). "Hence, the spontaneous onset of melanomas in cdkn2b+/- Xenopus tropicalis and the carcinogenic capacity of cdkn2b+/- remain to be further investigation in forthcoming studies." (PMID 39659584, 2024).
melanoma (continued). "Conversely, the incidence of spontaneous melanoma in 30-month-old cdkn2b-/- Xenopus tropicalis stands at 10%, suggesting that species-specific factors may contribute to observed phenotypic variations among related mouse, fish, and frog models." (PMID 39659584, 2024). "Interestingly, cdkn2b-/- Xenopus tropicalis also exhibit a propensity for spontaneous melanomas, with the incidence rising from 6% at 18 months to 10% at 30 months." (PMID 39659584, 2024). "Cyclin-dependent kinase-2a and 2b (CDKN2a-CDKN2b) are located in the INK4 locus on chromosome 9p21 and encode respectively for tumor suppressor p16 and p15, which act as CDK inhibitors, being associated with a predisposition to melanoma." (PMID 35008245, 2021). "ANRIL, the antisense lncRNA of the cyclin-dependent kinase inhibitor 2b (CDKN2B) gene, is involved in the development of the melanoma and neural system tumor syndrome, familial melanoma syndrome, and various tumor types; however, its association with PD has not yet been investigated." (PMID 29850016, 2018). "Alterations identified on the F1H panel included those among CDKN2A (p16/Ink4) and CDKN2B, which are well established in solid malignancies, including lung, breast, pancreatic, melanoma, and a variety of head and neck carcinomas, as well as in pre-B cell acute lymphoblastic leukemia (ALL)." (PMID 29899868, 2018). "There is in vitro evidence for a tumor suppressive role for CDKN2B in melanoma." (PMID 20140953, 2010). "Furthermore, the study suggests that within vertical growth phase melanoma, although loss impacting on CDKN2A was most frequent, wider deletions involving P14ARF and even CDKN2B were associated with poorer histological prognostic factors." (PMID 20140953, 2010). "More recently there has been some suggestion that CDKN2B may also have tumor suppressor functions in melanoma." (PMID 20140953, 2010).
melanoma (continued). "Patient B is a boy of 7 years when treated for astrocytoma then developing melanoma associated to congenital nevi on the head 10 years later: sequencing and multiplex ligation-dependent probe amplification revealed a normal profile of the CDKN2A/CDKN2B/CDKN2BAS region." (PMID 24884915, 2014). "In addition to the known tumor suppressor genes CDKN2A and CDKN2B, it was suggested that other genes and loci in this region may also be involved in melanoma and cutaneous nevi development." (PMID 23209811, 2012). "Only EMSY was recurrently affected by BA-SVs in both cutaneous and mucosal melanomas, and only CDKN2A and CDKN2B were recurrently affected by BA-SVs in both acral and cutaneous melanomas." (PMID 38758740, 2024). "Other than MTAP and SEPTIN5, CDKN2A, CDKN2B, HIRA, and DGCR8 were the only recurrently altered cutaneous melanoma genes that were not recurrently altered in acral or mucosal melanomas, which frequently lack the presence of UV-induced mutations." (PMID 38758740, 2024). "This study presents supportive evidence that CDKN2B, P14ARF, and CDKN2A may all play a tumor suppressor role in melanoma progression." (PMID 20140953, 2010). "A low incidence of mutations has been described for the CDKN2B gene in sporadic melanoma tumors; however, no structural defects have been detected in the CDKN1A gene in human melanoma." (PMID 15819981, 2005). "For CDKN2B we reviewed all two TSSs (FANTOM5-annotated clustered promoters) and found that the highest expression for this gene was in lens epithelial cells, preadipocytes, mesenchymal cells, cardiac fibroblasts, adipocytes, differentiated osteoblast, and melanoma cells." (PMID 35884374, 2022). "Second, CDKN2B-null mice showed a minimal cancer-prone phenotype and do not develop melanoma." (PMID 23816148, 2013). "By reviewing literature, only one Singaporean case with germline 9p21.3 deletion involving CDKN2A, CDKN2B, and partial MTAP and ANRIL genes had no melanoma but squamous cell carcinoma in the head and neck." (PMID 40046620, 2025).
breast carcinoma (35 papers, 2004 to 2025). "There was also some marginal evidence that the minor allele of rs1011970 near CDKN2A/CDKN2B was associated with increased breast cancer risk (HR = 1.09, 95% CI: 1.00 to 1.18, P-trend = 0.048)." (PMID 22348646, 2012). "In addition, a SNP located in a block encompassing CDKN2A and CDKN2B at 9p21, rs1011970, was reported to be associated with breast cancer in a recent genome-wide scan." (PMID 24915306, 2014). "Focal deletions involving Cdkn2a and Cdkn2b were found at chromosome 5q32 in 2 carcinomas (10%), as had been repeatedly observed in a subset of radiation-induced rat mammary carcinomas." (PMID 34388197, 2021). "The top five genes affected by methylation in breast carcinoma were involved with variable frequencies in the other tumor types, too, except for CDKN2B which was methylated in breast carcinoma only." (PMID 22691310, 2012). "The five most frequently methylated TSGs (RASSF1, APC, CDH13, GSTP1, and CDKN2B) were the same in all groups of breast cancer and, with the exception of CDKN2B, were involved in other tumors from LS patients, too, although with variable frequencies." (PMID 22691310, 2012). "Most of the prostate and breast-cancer cell lines studied had reduced copy number of CDKN2B gene, whereas in this study we found it upregulated with time after auraptene pretreatment." (PMID 23320178, 2012). "These include VTCN1 and CDKN2B, whose functional role in breast cancer downstream of this pathway requires further investigation." (PMID 18652687, 2008). "In addition, endoplasmic reticulum protein 29 suppresses breast cancer cell invasion by upregulating numerous genes, including CDKN2B, indicating that CDKN2B is involved in cell invasion." (PMID 25202407, 2014). "Thus, loss of C/EBPβ-mediated gene activation of Cdkn2b, as well as Cdh1 and Cxadr, shifts the TGF-β response in breast cancer cells from growth inhibition to EMT." (PMID 23955085, 2013). "The most frequently methylated genes were RASSF1 (65%), APC (43%), CDH13 (35%), GSTP1 (17%), and CDKN2B (17%), and the pattern was quite similar in breast carcinomas from mutation carriers, non-carriers and sporadic ductal cases." (PMID 22691310, 2012). "It has been shown that estradiol-induced PIM-1 overexpression in breast cancer leads to the phosphorylation of key proteins, which in turn suppresses the expression of cell cycle inhibitors (CDKN1A and CDKN2B)." (PMID 40565356, 2025). "The list of these genes includes not only a large number of known breast cancer genes (e.g. CDH1, CDH3, BMP4, MTAP, CDKN2B), revealed by previous studies using breast tumor tissues and breast cancer cell lines but also novel genes." (PMID 24885402, 2014). "Copy number aberrations (CNAs) in known breast cancer driver genes present in the PDTXs included gains/amplifications of MYC (78%), CCNE1 (34%), ZNF703 (25%), CCND1 (31%), MDM2 (25%), and ERBB2 (9%) and deletions of PTEN (41%), PPP2R2A (72%), CDKN2A (47%), and CDKN2B (47%)." (PMID 27641504, 2016). "Of note, the diminished expression of putative hub genes such as CDKN2B, CNNM4, LRRC19, and MOGAT2 might be the result of inactivation of genes through DNA methylation as their methylation was identified in colorectal, gastric, and breast cancers as well as in leukaemia." (PMID 29088818, 2017).